WIF1 (Wnt inhibitory factor 1)
Diseases named in the same sentence as WIF1 in open-access papers (continued):
Sharing a sentence is not in itself a finding about the gene and the disease.
tumor (continued). "Module-1 of the ENDCAP-C study showed that their panel of five markers (SFRP2, SFRP4, WIF1, APC1A, and APC2) was accurate in detecting pre-cancerous and invasive neoplasia and dysplasia." (PMID 34842672, 2021). "When the same analyses were done using PEA Oncology II profiling data, 10 proteins correlated to tumor stage (P < 0.05), for example, CD160, TNFRSF4/OX40L, XPNPEP2, SPARC, MAD homolog 5/SMAD5, CPE, hK8/KLK8, WIF‐1, TCL1A, and MIC‐A/B." (PMID 33768639, 2021). "For example, expression of HOTAIR and secreted Wnt antagonist WIF-1 is inversely correlated in ESCC cell lines and tumor tissues." (PMID 34488905, 2021). "Functional assay in numerous literatures provided further evidences supporting that some of the loci have close links with the modulation of tumor-suppressive mechanisms via regulation gene transcription (e.g., SFRP1 and WIF1)." (PMID 31959227, 2020). "In nasopharyngeal primary carcinoma cells, SFN inhibited tumor growth via the downregulation of DNMT1 and re-expression of the Wnt inhibitory factor 1 (WIF1)." (PMID 32878338, 2020). "Meanwhile, immunohistochemistry staining revealed that WIF‐1 expression was enhanced in propofol and siHOTAIR groups.Overall, these findings suggest that propofol or HOTAIR silencing inhibited tumor growth." (PMID 31953926, 2020). "In these models, the high level of tumor cell-specific beta-catenin signaling is accompanied by high-level production of Wnt inhibitors DKK1 and WIF1, which reprogram the intra-tumor vascular phenotype by inhibiting beta-catenin signaling in ECs." (PMID 30932813, 2019). "In the stage 2 analysis, five markers accurately discriminated between neoplasia and control samples with p < 0.0001 – SFRP2, SFRP4, WIF1, APC1A and APC2; with between 40% and 76% increases in geometric mean values." (PMID 30473377, 2019). "In adjacent non-tumor tissues, the number of patients with SFRP1, SFRP2, and WIF1 methylation levels exceeding the cut-off value were 5 (2.7%), 7 (3.7%) and 41 (21.9%), respectively." (PMID 31830937, 2019). "Interestingly, we mapped a putative TRE within the promoter of the human WIF1 gene, suggesting that a similar mechanism of transcriptional regulation by TRα1 is present in mouse and in human Wif1/WIF1 promoters, also in accordance with the analysis of the tumor cohorts." (PMID 30123421, 2018). "In this study, we found promoter methylated WIF1 in both CS cell lines (CS-1 and SW1353) and tumor tissues." (PMID 28484252, 2017). "To investigate the efficacy of MRx102 on patient tumor tissue, we subcutaneously implanted NSCLC tissue from patients with either low or high WIF1 expressing tumors by RT-PCR and western blot analysis into NSG mice." (PMID 27400883, 2016). "WNT inhibitory factor 1 (WIF1), as another tumor suppressor gene, has been found to be epigenetically silenced in various cancers including NSCLC32." (PMID 25754026, 2015). "Additionally, the distribution of WIF1 positive cells at the hyperplasic stage (4–6 weeks) was quite different from that at the carcinoma stage (12 weeks); specifically, WIF1 localization changed from primarily the outer layer of lesions to being distributed throughout the entire tumor." (PMID 25918249, 2015). "We used two multiplex assays, namely Alb-Fam/WIF1-Vic and the NPY-Ned/PENK-Vic, to measure methylation of our three biomarkers in a set of 15 paired normal and tumor tissue samples." (PMID 24289328, 2013). "Re-expression of WIF1 in a bone metastatic PCa cell line, PC3, resulted in an in vivo inhibition of tumor growth and a decreased capacity of cell migration and invasion." (PMID 20573255, 2010). "Thus, it is reasonable to speculate that WIF1 may have an anti-angiogenesis effect on tumor growth." (PMID 20573255, 2010). "Two antagonists of WNT receptor signaling, WIF1 and secreted frizzled-related protein 1 (SFRP1), were downregulated in both the tumor epithelium and the stroma." (PMID 19187537, 2009).
tumor (continued). "Two antagonists of WNT receptor signaling, WIF1 and SFRP1, were consistently downregulated both in the tumor epithelium and stroma." (PMID 19187537, 2009). "It was previously reported that expression of the Wnt antagonist genes WIF1 and DKK3 is downregulated in several tumor entities as a consequence of epigenetic DNA modification." (PMID 19570204, 2009). "CpG island methylation of both WIF1 and ESR1 genes made a significant contribution to the distinction between the normal mucosa of cancer patients and that of neoplasia-free patients." (PMID 18542073, 2008). "The level of methylation was significantly lower in normal-appearing cancer mucosa compared with neoplasia-free mucosa for ESR1, MINT31 and WIF1." (PMID 18542073, 2008). "Additionally, hypermethylation of the Wnt inhibitory factor 1 (WIF1) gene has been observed in CS cell lines (CS-1 and SW1353) and tumor tissues." (PMID 40867318, 2025). "The coordinated downregulation of KLF4, OLR1, CSF3, WIF1, RAMP3, and AGER, may impair tumor-suppressive mechanisms, thereby facilitating cancer progression, including enhanced tumor growth, migration, invasion, and metastasis." (PMID 40797277, 2025). "Overexpression of WIF-1 enhances RCC cell apoptosis and inhibits tumor growth in vivo." (PMID 36910160, 2023). "Moreover, in our study, we investigated the association between miR-181a-5p and miR-630 target genes (BCL2, LMO3, PTEN, SNAI2, WIF1) expression and clinicopathological characteristics as well as survival rates of NSCLC patients in tumor tissue." (PMID 37697308, 2023). "Huang L., Li M.X., Wang L., Li B.K., Chen G.H., He L.R., Xu L.,Yuan Y.F. Prognostic value of Wnt inhibitory factor-1 expression inhepatocellular carcinoma that is independent of gene methylation.Tumour Biol." (PMID 36714033, 2022). "Wnt inhibitory factor-1(WIF1) is a Wnt antagonist and tumor suppressor." (PMID 36550577, 2022). "Studies have reported that WIF1, as a secreted antagonist of Wnt proteins and an inhibitor of the Wnt signaling pathway, is a tumor suppressor in various malignancies; nevertheless, the mechanism of WIF1 in BC has not been fully clarified." (PMID 35372039, 2022). "Wnt inhibitory factor 1 (WIF1) can interact with the Wnt protein to inhibit the canonical and non-canonical Wnt pathways to exert tumor inhibitory effect." (PMID 36618366, 2022). "WIF1 overexpression was found to inhibit the growth, proliferation, and keratinization of allografts of ASZ001 cells exclusively in vivo, but not in culture, indicating that WIF1-mediated changes require cofactors available in the tumor microenvironment." (PMID 34944004, 2021). "The local cohort study confirmed that NPY and WIF1 were significantly hypermethylated in tumor tissues compared to adjacent non-tumor tissues (WIF1 p < 0.001; NPY p < 0.001; non-parametric Wilcoxon paired-series test)." (PMID 34627187, 2021). "Moreover, DNA methylation downregulated the expression of Wnt inhibitors including Wnt inhibitory factor 1 (WIF-1), several frizzled-related proteins (SFRP1-5), and Dickkopf-related protein 1 (DKK1) in the tumor cells." (PMID 34051847, 2021). "Propofol may exert similar inhibitory effect on in vivo tumor metastasis, and this effect was probably due to the reduced expression of STAT3, HOTAIR, and WIF‐1 expression and subsequent activation of Wnt signaling pathway." (PMID 31953926, 2020). "The cut-off values of SFRP1, SFRP2, and WIF1 methylation were 10.0, 5.0 and 20.0%, respectively, which had high predictive ability to distinguish tumor tissues from adjacent non-tumor tissues." (PMID 31830937, 2019). "We had detected the methylation of SFRP1, SFRP2, and WIF1 for 187 adjacent non-tumor tissue specimens and 307 primary tumor tissue specimens." (PMID 31830937, 2019).
tumor (continued). "Three proteins and two clinical signatures were confirmed to be significantly related to the regrowth of NFPA, including cyclin-dependent kinase inhibitor 2A (CDKN2A/p16), WNT inhibitory factor 1 (WIF1), tumour growth factor beta (TGF-β), age and tumour volume." (PMID 31109334, 2019). "The cg04255616 probe (SFRP1), cg25185173 probe (SFRP2), and WIF1 methylation levels of adjacent non-tumor tissues were significantly lower than those of tumor tissues (Mann-Whitney U test, P < 0.001)." (PMID 31830937, 2019). "The Cancer Genome Atlas (TCGA) database also validated WIF1 methylation in tumor tissues was significantly higher than that in non-tumor adjacent tissues." (PMID 29435185, 2018). "Cluster analysis showed MBCs arising in BRCA2 mutation carriers were characterised by RASSF1A, WIF1, RARβ and GTSP1 methylation (p = 0.02) whereas methylation in BRCAX tumours showed no clear clustering to particular genes." (PMID 28893223, 2017). "Moreover, in Hu’s study, it was shown that Wnt antagonists WIF1-Fc and SFRP1-Fc inhibit Wnt signalling and exert antitumour activity by inducing apoptosis in tumour cells, which indicates that Wnt antagonists would be a promising molecular treatment for HCC." (PMID 28899352, 2017). "To date, the high CpG island methylation intensity of some tumor suppressors, RASSF1A, WIF1, DAPK1 and RARβ2, have been assessed by MS-HRM assays in NPC, so it is necessary to define whether DNA methylation of these promoters is also mediated by LMP1." (PMID 27223069, 2016). "However, WIF1 expression was significantly attenuated in MMTV-PyMT mice, particularly after tumor development." (PMID 25918249, 2015). "Eleven cancer related genes were found to have methylation (defined as more than 10 % methylation) in at least some of the tumours: RASSF1A (64 %), TWIST1 (61 %), CDH13 (51 %), APC (50 %), MAL (35 %), GSTP1 (30 %), WIF1 (26 %), RARβ (19 %), BRCA1 (2 %), CDKN2A (2 %) and TP73 (2 %)." (PMID 26452468, 2015). "Unlike SFRPs, there is little evidence to support the role of WIF-1 as a tumor suppressor at present." (PMID 24949429, 2014). "Tumor samples from 155 patients with stages IIIB to IV NSCLC who received EGFR-TKI therapy were analyzed for DNA methylation status of Wnt antagonist genes, including SFRP1, SFRP2, SFRP5, DKK3, WIF1, and APC, using methylation specific PCR (MSP) method." (PMID 23009178, 2012). "In addition, overexpression of circRNA-0030167 in MSC exosomes was reported to inhibit miR-338-5p expression, promote the expression of WNT inhibitory factor 1 (WIF1), and inhibit the WNT8/β-catenin pathway, thereby inhibiting the stemness and tumor progression of PDAC." (PMID 36076911, 2022). "Our observation that the human WIF1 protein is a potent antagonist of human Shh suggests that the known tumor suppressor activity of WIF1 may not be ascribed only to its role as a Wnt inhibitor." (PMID 34944004, 2021). "Our observation that the human WIF1 protein is a potent antagonist of Shh suggests that the known tumor suppressor activity of WIF1 may not be ascribed only to its role as a Wnt inhibitor." (PMID 34944004, 2021). "It was found that a miR-181a gene target, WiF-1 (Wnt inhibitory factor 1), leads to a potent liver metastasis effect by suppressing epithelial markers such as E-cadherin and β-catenin and by overexpressing the mesenchymal marker vimentin found in CRC tumor tissues with liver metastasis." (PMID 32974184, 2020). "Nevertheless, WIF1 methylation test is not tumor specific, being WIF1 methylated in normal colon mucosa as well, suggesting that the use of a broader panel of methylated loci would be more compliant to liquid biopsy analyses to improve the positivity of ctDNA detection." (PMID 33291569, 2020). "As a total of 307 sporadic postoperative CRC patients were followed up, we detected SFRP1, SFRP2, and WIF1 methylation obtained from tumor tissues and adjacent non-tumor tissues respectively on the basis of methylation-sensitive high resolution melting analysis." (PMID 31830937, 2019).
tumor (continued). "Finally, consistent with mRNA expression levels, the WIF1 protein was not detectable in vil-TRα1/Apc tumor sections but resulted more widely expressed in TRα0/0/Apc tumors." (PMID 30123421, 2018). "This is confirmed in tumor DNA extracted from a biopsy for which no methylation of the MLH1 gene promoter was found, whereas methylation of the NPY and WIF1 genes was observed." (PMID 34627187, 2021). "The same absence is observed with the tumor stage (p = 0.2873 for NPY; p = 0.0517 for WIF1; non-parametric Kruskal-Wallis test, n = 22)." (PMID 34627187, 2021). "Immunohistochemical analysis shows that tumor sections from the WIF1 transfected PC3 cell line exhibited a marked increase in E-cadherin and Keratin-18 while tumor sections from vector control cell line revealed no or very weak staining." (PMID 20573255, 2010). "Importantly, significant hypermethylation of both genes was demonstrated in tumor tissues compared to adjacent non-tumor tissues (NPY p = 0.001; WIF1 p = 0.002; non-parametric Wilcoxon paired-series test)." (PMID 34627187, 2021). "The analysis of the corresponding tumor and non-tumor samples also revealed upregulation of COMP, matrix proteins such as COL5A1, COL11A1, and FN1, and genes of the Wnt pathway (WNT7B, FZD10, SFRP2), while PLCB1, CAMK2B, PLCB4 and WIF1 are downregulated." (PMID 33227073, 2020).
cancer (95 papers, 2008 to 2025). A tumor composed of atypical neoplastic, often pleomorphic cells that invade other tissues. "Epigenetic silencing of WIF-1 was shown to be an important mechanism causing aberrant activation of the Wnt/β-catenin pathway in several human cancers." (PMID 32650720, 2020). "ALDH1L1 and WIF1 have been shown to be ubiquitously downregulated in cancers, and their downregulation was associated with poor clinical outcomes in cancer." (PMID 28427185, 2017). "Methylation of the WIF-1 gene can lead to the loss of WIF-1 expression which has been observed in numerous types of cancer including NSCLC." (PMID 27911280, 2017). "WIF-1, a Wnt antagonist, is implicated in inhibiting metastasis and tumorigenesis in multiple cancers and is often epigenetically silenced in CC, affecting apoptosis and cancer growth." (PMID 38835778, 2024). "In numerous human cancers, WIF1 promoter hypermethylation was linked to a poor prognosis." (PMID 36619866, 2022). "Activation of β-catenin by miR-221 and miR-222 promotes estrogen-independent growth of cancer cells, whereas Wnt-inhibitory factor-1 (WIF1) is suppressed by these miRNAs." (PMID 38365810, 2024). "Owing to its biological function, interest in using WIF1 as a biomarker for the early detection, diagnosis, and prognosis of cancer has increased in recent years." (PMID 36012492, 2022). "A possible mechanism for cancer to resist or to minimize the effects of the defense mechanism of the cell would be to upregulate a competitor of WIF1 to ultimately activate the Wnt pathway." (PMID 33891491, 2021). "In summary, these results indicated that CRBP-1 inhibited Wnt/β-catenin pathway via upregulating WIF1, then suppressed cancer stemness properties in HCC." (PMID 34775955, 2021). "To determine the mechanism by which HOTAIR regulates the expression of genes associated with cartilage catabolism and anabolism in OA, we investigated WIF-1 due to its known interactions with HOTAIR in cancer progression." (PMID 32650720, 2020). "WNT inhibitory factor-1 (WIF-1) is a pivotal antagonist of β-catenin signaling pathway and frequently inactivated via DNA hypermethylation in human cancers." (PMID 31217782, 2019). "Western blot analysis confirmed that UNC0638 treatment dramatically reduced the level of H3K9Me2, increased the levels of APC2, DKK1, and WIF1 proteins, and resulted in decreased β-catenin in these cancer cells." (PMID 30348169, 2018). "For instance, targeted disruption or addition of CpG islands in the Wif1 promoter using genome editing techniques would be informative with respect to the resulting cell behaviors in established Wnt cancer models." (PMID 30574494, 2018). "Epigenetic silencing of the Wif1 promoter is a common feature, frequently resulting in cancer progression when uncontrolled." (PMID 30574494, 2018). "A target gene WIF1 stands out by the proposed method, which indeed is verified as a frequent target for epigenetic silencing in various human cancers." (PMID 30591011, 2018). "Epigenetic promoter methylation of Wif1, leading to silencing of its transcription and concomitant up-regulation of Wnt signaling, is a common feature during cancer progression." (PMID 30574494, 2018). "Aberrant DNA methylation in the promoter CpG island of Wnt inhibitory factor 1 (WIF1) has been observed in different cancers." (PMID 28484252, 2017). "Repression of the Wnt pathway by extracellular inhibitors, such as Dickkopf1 (DKK1), Wnt inhibitory factor 1 (WIF1), or secreted frizzled-related proteins (SFRPs), has also been observed in human cancers." (PMID 27713747, 2016). "Restoring WIF1 levels by modifying its DNA methylation patterns has been suggested as an anti-cancer strategy in other malignancies." (PMID 25918249, 2015). "Several cancer-promoting genes were uperegulated (Ctgf, H19, Mmp12, Mybl1, Vnn1) while cancer inhibiting genes (Cish, Dkk4, Onecut1, Scara5, Socs3, Wif1) were suppressed." (PMID 26200659, 2015).